PDGFB (platelet derived growth factor subunit B)
Diseases named in the same sentence as PDGFB in open-access papers (continued):
Sharing a sentence is not in itself a finding about the gene and the disease.
endometriosis (2 papers, 2022 to 2024). The growth of functional endometrial tissue in anatomic sites outside the uterine body. "In another empirical study, we indicated that endometriosis is characterized by an upregulation in the expression of the PDGFB and EGF at the gene level." (PMID 38698459, 2024). "Notably, we showed that vitamin D3 significantly reduced PDGFB and EGF gene expression, indicating that vitamin D supplementation might be a therapeutic approach to managing endometriosis." (PMID 38698459, 2024).
Headache (2 papers, 2022 to 2024). Cephalgia, or pain sensed in various parts of the head, not confined to the area of distribution of any nerve. "In the present study, it was repeatedly stated that patients with PDGFB variants suffer from headaches such as "pain from heartbeats" and "temple tightening" from a young age, and even analgesics do not relieve these symptoms." (PMID 36206226, 2022). "A systematic review of FIBGC reported that headaches are more common in PDGFB (32.5% of cases), and parkinsonism is more common in SLC20A2 (21% of cases)." (PMID 36206226, 2022).
idiopathic pulmonary arterial hypertension (2 papers, 2020 to 2024). A sporadic form of pulmonary arterial hypertension (PAH) characterized by elevated pulmonary arterial resistance leading to right heart failure. "The levels of Twist1 and PDGFB are higher in PAE cells isolated from idiopathic pulmonary arterial hypertension (IPAH) patients compared to those from healthy controls." (PMID 32371931, 2020).
kidney cancer (2 papers, 2017 to 2021). Primary or metastatic malignant neoplasm involving the kidney. "In kidney cancer, KLF6-SE promotes the expression of KLF6 and then activates PDGFB to promote lipid metabolism, leading to the growth of ccRCC25." (PMID 33712565, 2021).
leiomyosarcoma (2 papers, 2013 to 2023). An uncommon, aggressive malignant smooth muscle neoplasm, usually occurring in post-menopausal women. "Finally, we confirmed the expected overexpression of some genes: KIT and ANO1/DOG1 in GISTs, MDM2 and CDK4 in non-myxoid/round cells liposarcomas, CALD1 and tropomyosin genes (TPM1, TPM2) in leiomyosarcomas, PDGFB in DFSPs, MUC1/EMA in synovial sarcomas, and CD34 in SFTs." (PMID 23734203, 2013).
liposarcoma (2 papers, 2013 to 2025). A usually painless malignant tumor that arises from adipose tissue. "Fluorescence in situ hybridization (FISH) confirmed no PDGFB (22q13) translocation or COL1A1::PDGFB fusion, which are common in DFSP, and no MDM2 amplification, typically seen in liposarcomas." (PMID 40556675, 2025).
liver disease (2 papers, 2023 to 2024). "The TGFB- and PDGFB-induced fibrosis in microHOs was shown to resemble human fibrotic liver disease based upon the formation of thick collagen fibers (SHG results), and these agents increased collagen cross-linking (4-OHPro measurement) and collagen deposition (trichrome staining) in microHOs." (PMID 39656528, 2024). "Notably, the dataset includes many known proteins (IL6, IL10, IFNG, CSF3, PDGFB, CD40, and AFP) and novel proteins associated with liver diseases." (PMID 37209815, 2023).
lung carcinoma (2 papers, 2015 to 2024). "used a weighted gene co-expression network analysis screening method to identify four key genes that are shared with OSA and lung cancer, namely modulator of apoptosis 1 (MOAP1), chromobox 7 (CBX7), platelet-derived growth factor subunit B (PDGFB), and mitogen-activated protein kinase 3 (MAP2K3)." (PMID 38605948, 2024).
lung diseases (2 papers, 2023 to 2024). "Accordingly, genetically enhancing ZNF451 expression or neutralizing PDGFB with a PDGFB-neutralizing antibody may represent a novel therapeutic strategy for PF and other fibroproliferative lung diseases." (PMID 38600524, 2024).
migraine (2 papers, 2020 to 2022). "Mutations in PDGFB cause brain calcification disorders and; interestingly, it has been shown that migraine is commonly present in the mutation carriers." (PMID 35546551, 2022). "Lastly, our scan for inferring causality identified five blood proteins (DKK1, PDGFB, GSTA4, FARS2 and CHIC2) with a significant genetic causality on migraine." (PMID 35546551, 2022). "Taken together, our current results suggest DKK1 and PDGFB as two promising therapeutic targets against migraine." (PMID 35546551, 2022). "We show that higher levels of DKK1 and PDGFB, and lower levels of FARS2, GSTA4 and CHIC2 proteins have a significant causal effect on migraine." (PMID 35546551, 2022). "The LCV analyses found a significant genetic causality on migraine for higher levels of two blood proteins, DKK1 and PDGFB." (PMID 35546551, 2022). "In addition, we identified that higher levels of DKK1 and PDGFB, and lower levels of FARS2, GSTA4 and CHIC2 causally increase the risk of migraine." (PMID 35546551, 2022).
neuroblastoma (2 papers, 2023 to 2024). Neuroblastoma (NB) is the most common solid, extracranial childhood tumor. "Additionally, while the elevated PDGFB and TGFB signaling in patient samples is likely due to the stromal and immune cells 41, it is possible activation of these signaling pathways could improve the efficiency of generating SA cells and neuroblastoma tumors." (PMID 39367051, 2024).
Parkinsonism (2 papers, 2022 to 2023). Characteristic neurologic anomaly resulting from degeneration of dopamine-generating cells in the substantia nigra, a region of the midbrain, characterized clinically by shaking, rigidity, slowness of movement and difficulty with walking and gait. "Parkinsonism is present in up to 80% of subjects with JAM2, in about 30% of cases of XPR1, SLC20A2, MYORG, and less frequently in PDGFB, PDGFRB mutation carriers." (PMID 37240341, 2023).
Sepsis (2 papers, 2020 to 2024). Sepsis is defined as life-threatening organ dysfunction caused by a dysregulated host response to infection. "A high level of platelet-derived growth factor B (PDGFB) is found in survivors of sepsis, and PDGFB can reduce the mortality of sepsis by blocking inflammatory responses." (PMID 32174955, 2020).
Thrombocytopenia (2 papers, 2013 to 2021). A reduction in the number of circulating thrombocytes. "The complex network constructed for SOFA criterion 6 (low platelet count) included downregulated PDGFB signaling by the upregulated miR-30c-5p (PDGFB knock-out mice showed thrombocytopenia)." (PMID 34573990, 2021). "The good correlation between platelet count and PDGFB expression suggests that thrombocytopenia in cirrhotic patients may have an impact on PDGFB secretion thereby influencing gastric ulcer healing." (PMID 23620752, 2013). "These diminished expressions of PDGFB, VEGFR2, FGFR1, and FGFR2 were well correlated with the degree of thrombocytopenia in the cirrhotic patients." (PMID 23620752, 2013). "Diminished expressions of PDGFB and VEGFR2, FGFR1, and FGFR2 were well correlated with the degree of thrombocytopenia in these cirrhotic patients (ρ>0.5, p<0.001)." (PMID 23620752, 2013). "We found that diminished mRNA expressions of proangiogenic growth factors (PDGFB) and their receptors (VEGFR2, FGFR1, and FGFR2) in gastric ulcer margins were well correlated with the degree of thrombocytopenia in the cirrhotic patients." (PMID 23620752, 2013).
uveal melanoma (2 papers, 2020 to 2025). A melanoma derived from melanocytes of the uveal tract. "These uveal melanoma patients exhibit an increase in the expression of classic and well-documented hypoxia-dependent genes such as PDGFB, LOXL2, VEGF, ANGPT2, KDR, and S1PR1." (PMID 40000790, 2025).
abscess (1 paper, 2021). An inflammatory process characterized by the accumulation of pus within a newly formed tissue cavity which is the result of a bacterial, fungal, or parasitic infection or the presence of a foreign body. "The proteins HGF and PDGFB were both involved in fibrosis, which is especially interesting given that fibrosis is required to encapsulate the SAC and immune cells around SAC to form an abscess." (PMID 34832602, 2021).
acute myeloid leukemia (1 paper, 2022). Acute myeloid leukemia (AML) is a group of neoplasms arising from precursor cells committed to the myeloid cell-line differentiation. "It is worth to mention that a few genes with a role in acute myeloid leukemia: GRB2, CSFIR, MARCKS and PDGFB were upregulated; FLT1, IL6, PIK3C2B, BALAP3 and MAPK10 were downregulated." (PMID 36413544, 2022).
adrenocortical adenomas (1 paper, 2018). "Moreover, PDGFD is highly expressed in human adrenal gland, unlike PDGFA, PDGFB, and PDGFC, and the expression of PDGFD correlates negatively with cortisol secretion in adrenocortical adenomas." (PMID 29551627, 2018).
AIDS (1 paper, 2018). A syndrome resulting from the acquired deficiency of cellular immunity caused by the human immunodeficiency virus (HIV). "We found that KSHV-LANA staining appears in areas corresponding to phosphorylated PDGFRA, as well as, diffuse PDGFA and PDGFB expression in mECK36 tumors and in AIDS-KS lesions." (PMID 29985958, 2018). "The existence of a KSHV-induced, ligand-mediated mechanism for PDGFRA activation is supported by immunohistochemistry staining of mECK36 and AIDS-KS lesions showing that the areas staining for both KSHV-LANA and phospho-PDGFRA correspond with the detection of PDGFRA ligands PDGFA and PDGFB." (PMID 29985958, 2018).
anaplastic oligodendroglioma (1 paper, 2016). A WHO grade III oligodendroglioma with focal or diffuse malignant morphologic features (prominent nuclear pleomorphism, mitoses, and increased cellularity). "PDGFB-expression induces tumors with features similar to human grade II diffuse oligodendroglioma or grade III anaplastic oligodendroglioma in G/tv-a wt mice." (PMID 27806344, 2016).
anaplastic thyroid cancer (1 paper, 2016). "Reinforcing our observations regarding the relationship of LETM1 with cellular growth signaling, LETM1 silencing resulted in decreased protein levels of PDGFB and mRNA expression of PDGFB, PDGFBR and THBS4 in BCPAP cells and 8505C cells (human anaplastic thyroid cancer cell line)." (PMID 27556512, 2016).
and neck cancer (1 paper, 2024). "and neck cancer (HNC), the invasion-associated molecules LAMA3, LAMC2, THBS1, IGF1R, PDGFB, and transforming growth factor β1 can serve as prognostic indicators or molecular therapeutic targets to improve the survival rates of HNC." (PMID 38877482, 2024).
cervical cancer (1 paper, 2019). A primary or metastatic malignant neoplasm involving the cervix. "The genes encoding VGEF, RRAS2, PRKCB, RASGRP, and PDGFB involved in the six cell-signaling pathways are not currently reported in cervical cancer; however, they were reported as overexpressed in other carcinomas, suggesting their participation in carcinogenesis." (PMID 30696040, 2019).
cholangiocarcinoma (1 paper, 2024). A carcinoma that arises from the intrahepatic biliary tree (intrahepatic cholangiocarcinoma) or from the junction, or adjacent to the junction, of the right and left hepatic ducts (hilar cholangiocarcinoma). "The database showed that both PDGFB and PDGFRB were highly expressed in Cholangiocarcinoma (CHOL), Liver hepatocellular carcinoma (LIHC), Lymphoid Neoplasm Diffuse Large B-cell Lymphoma (DLBC), Pancreatic adenocarcinoma (PAAD and Head and Neck squamous cell carcinoma (HNSC)." (PMID 37307823, 2024).
Cirrhosis (1 paper, 2024). A chronic disorder of the liver in which liver tissue becomes scarred and is partially replaced by regenerative nodules and fibrotic tissue resulting in loss of liver function. "In contrast, PDGFB was mainly expressed in ECs, and increased and slightly increased in ECs1 and KCs, respectively, in cirrhosis livers." (PMID 39394459, 2024).
cognitive decline (1 paper, 2019). "Recently, mutations in four different genes (SLC20A2, PDGFRB, PDGFB, and XPR1) were identified, together with novel mutations in the Myogenic Regulating Glycosylase gene, causing the occurrence of movement disorders, cognitive decline, and psychiatric symptoms." (PMID 31267306, 2019).
Coronary Artery Disease (1 paper, 2016). "The aim of this paper was to analyse the relationship between polymorphisms in the TGFB1, PDGFB, bFGF, EGF and VEGF-A genes and ISR in patients with stable coronary artery disease (SCAD)." (PMID 26930482, 2016).
Crohn disease (1 paper, 2013). A gastrointestinal disorder characterized by chronic inflammation involving all layers of the intestinal wall, noncaseating granulomas affecting the intestinal wall and regional lymph nodes, and transmural fibrosis. "A PBC associated SNP (rs968451) near PDGFB were in close linkage disequilibrium with rs2413583, which is associated with IBD and Crohn's disease." (PMID 27896059, 2013).
endometrial disorder (1 paper, 2025). A non-neoplastic or neoplastic disorder that affects the endometrium. "In contrast, reduced PDGFB expression has been observed in endometrial endothelial cells of women with abnormal uterine bleeding linked to endometrial disorders." (PMID 41300775, 2025).
esophageal squamous cell carcinoma (1 paper, 2024). Esophageal squamous cell carcinoma (ESCC) is a type of esophageal carcinoma (EC) that can affect any part of the esophagus, but is usually located in the upper or middle third. "Targeting PDGFB reduced cancer cell growth and increased radiation sensitivity, suggesting the potential of PDGF-BB as a predictive marker for esophageal squamous cell carcinoma radiotherapy response." (PMID 38672104, 2024).
essential thrombocythemia (1 paper, 2020). A chronic myeloproliferative neoplasm that involves primarily the megakaryocytic lineage. "The expression level of PDGFB and PDGFRB in the bone marrow of essential thrombocythemia patients were significantly higher than in normal controls." (PMID 32235327, 2020).
gastric ulcer (1 paper, 2013). An ulcerated lesion in the mucosal surface of the stomach. "The cirrhotic patients had diminished mRNA expressions of PDGFB, VEGFR2, FGFR1, and FGFR2 in gastric ulcer margin when compared with those of the non-cirrhotic patients (p<0.05)." (PMID 23620752, 2013). "We found that cirrhotic patients had diminished mRNA expressions of proangiogenic growth factors (PDGFB) and their receptors (VEGFR2, FGFR1, and FGFR2) in gastric ulcer margins compared with those of the non-cirrhotic patients." (PMID 23620752, 2013).
germ cell neoplasm (1 paper, 1991). "In comparison with normal DNA, tumour DNA of a total of eight patients (seven with germ cell neoplasm and one with testicular lymphoma) showed increased dosages of KRAS2, PDGFA, EGFR, MET and PDGFB." (PMID 1829952, 1991).
hemangioma (1 paper, 2021). A benign vascular lesion characterized by the formation of capillary-sized or cavernous vascular channels. "They proved that PDGFB and PDGFRβ signaling plays a role in hemangioma pathogenesis." (PMID 33400686, 2021). "In addition, data from a separate study demonstrated that PDGFB and PDGFRβ signaling might act as an intrinsic negative regulator of hemangioma involution." (PMID 33400686, 2021).
hypereosinophilic syndrome (1 paper, 2010). Hypereosinophilic syndrome (HES) constitutes a rare and heterogeneous group of disorders, defined as persistent and marked blood eosinophilia and/or tissue eosinophilia associated with a wide range of clinical manifestations reflecting eosinophil-induced tissue/organ damage. "However, a PDGFRA mutation was associated with Gleevac-sensitive hypereosinophilic syndrome (HES), so perhaps decreased PDGFB-related transcription is also associated with an eosinophilic response." (PMID 20625511, 2010).
Leukoencephalopathy (1 paper, 2017). This term describes abnormality of the white matter of the cerebrum resulting from damage to the myelin sheaths of nerve cells. "In addition, a partial intragenic large deletion within PDGFB, c.161-238_602-676del441 (p.Glu54Aladel147) has been reported in a patient with brain calcification and leukoencephalopathy, indicating a loss-of-function mechanism for PDGFB-related PFBC30." (PMID 28935882, 2017).
meningitis (1 paper, 2025). A disorder characterized by acute inflammation of the meninges of the brain and/or spinal cord. "A2M, ADA2, and PDGFB, as cytokine receptors, displayed higher or lower levels compared to the other three meningitis types." (PMID 41181321, 2025).
orbital neoplasm (1 paper, 2015). "The association of PDGFB gene with the orbital neoplasm has been reported." (PMID 25924890, 2015).
oropharyngeal cancer (1 paper, 2020). Carcinoma, predominantly squamous cell, arising from the epithelial cells of the oropharynx. "PDGFB binds to PDGFRB and is speculated to play a crucial role in the tumorigenesis of oropharyngeal cancer." (PMID 32235327, 2020).
pancreatic neuroendocrine carcinoma (1 paper, 2022). "By crossbreeding the pl-PDGFB KO mice to the spontaneous RIP1-Tag2 (RT2) model for pancreatic neuroendocrine carcinoma, we identified a previously unknown role for platelet-derived PDGFB in the pericyte recruitment to tumor vessels and maintenance of vascular integrity." (PMID 35454853, 2022). "To this end, we made use of a mouse model with conditional deletion of PDGFB in platelets, which was crossbred to the RIP1-Tag2 model for pancreatic neuroendocrine carcinoma." (PMID 35454853, 2022).
parasite infections (1 paper, 2025). "Our GO enrichment analysis shows that response to stimulus is the most significantly enriched biological process, which is highly consistent with host immune response mechanisms triggered by parasite infections, in which the core genes TNF, STAT3, STAT5A, PDGFB, ADRB2 and SMO were included." (PMID 41153368, 2025). "Currently, PDGFB is generally not considered a direct anti-parasitic molecule, but it plays an important supportive role in maintaining host defense mechanisms and tissue integrity, and its expression and function are indeed affected by parasitic infections." (PMID 41153368, 2025).
persistent fetal vasculature syndrome (1 paper, 2012). "Patients with persistent fetal vasculature syndrome (PFVS) display similar problems with a large individual variability that was also seen among the nes/tk-PdgfB-lacZ mice." (PMID 22880002, 2012).
phyllodes tumor (1 paper, 2025). A benign, borderline, or malignant fibroepithelial neoplasm arising from the breast and rarely the prostate gland.
pituitary tumor (1 paper, 2022). A benign or malignant neoplasm affecting the pituitary gland. "PDGFB expression in all types of pituitary tumors was, on average, 10.5-fold (p<0.0001) greater than that of normal pituitary tissue." (PMID 35600354, 2022). "The expression of PDGFA, PDGFB, TGFB1 and TGFB2 in pituitary tumor tissue was respectively 3.5 x104, 2.0 x 104, 1.3 x 105 and 6.6 x 103 copies/μg total RNA." (PMID 35600354, 2022). "Pituitary tumors also expressed significantly higher levels of angiogenesis growth factors, including VEGFA (4.2-fold), VEGFB (2.2), VEGFC (19.3), PGF (13.4), ANGPT2 (9.2), PDGFA (2.7), PDGFB (10.5) and TGFB1 (3.8) compared to normal pituitary tissue." (PMID 35600354, 2022).
polycystic ovary syndrome (1 paper, 2023). A disorder that manifests as multiple cysts on the ovaries. "PDGFB and PDGFD decreased in the follicular fluid of PCOS patients, while ovarian administration restored follicular development and angiogenesis in a rat model of polycystic ovary syndrome." (PMID 37122871, 2023).
postmenopausal osteoporosis (1 paper, 2022). Metabolic disorder associated with fractures of the femoral neck, vertebrae, and distal forearm. "Moreover, as a homodimer of PDGFB, plasma PDGF-BB levels are maintained by estrogen in healthy young women and play a major role in postmenopausal osteoporosis." (PMID 35580864, 2022).